PNMA6E (PNMA family member 6E)
Gene: Protein-coding gene on chromosome X (153,395,639 to 153,401,392, reverse strand). Ensembl gene ENSG00000214897.
Homologues: Orthologues: macaque PNMA6E (81% identical), mouse Pnma6e (52% identical), rat Pnma6e (52% identical), mouse Gm45015 (15% identical). Paralogues in human: PNMA6F (68% identical), PNMA6A (28% identical), PNMA3 (23% identical), PNMA5 (22% identical), PNMA2 (21% identical), MOAP1 (21% identical), PNMA1 (20% identical), PNMA8A (15% identical), ZCCHC18 (14% identical), ZCCHC12 (13% identical), PNMA8B (13% identical), CCDC8 (11% identical), and 1 more.
Diseases named in the same sentence as PNMA6E in open-access papers:
PNMA6E is named in the same sentence as 2 diseases in open-access papers, as found by Europe PMC text mining. Sharing a sentence is not in itself a finding about the gene and the disease. The quoted sentences say what the papers report.
colorectal cancer (1 paper, 2023). A primary or metastatic malignant neoplasm that affects the colon or rectum. "Our RNA-Seq analysis also found that 5’-Aza-CdR exposure resulted in overexpression of multiple CT antigens in gastric cancer and colorectal cancer, including SSX1, TKTL1, SPANXB1, PNMA5, PNMA6E, GAGE12J, and PRSS56." (PMID 37400936, 2023).
PNMA6E also shares sentences with these, for which no sentence is quoted: gastric cancer (1 paper).